TNF (tumor necrosis factor)
Diseases named in the same sentence as TNF in open-access papers (continued):
Sharing a sentence is not in itself a finding about the gene and the disease.
gout (continued). "In contrast, neither MSU crystal injection nor CAPE treatment altered TNF-α levels, indicating that TNF-α may not play an important role in the inflammatory symptoms of uric acid crystal-induced gout." (PMID 27934918, 2016).
co-infection (180 papers, 2008 to 2026). "EBV coinfection intensified this phenotype, being associated with elevated levels of IL-6, IL-10, IL-15, TNF-α, and sCD40L, and with greater loss of memory cell subpopulations." (PMID 41929504, 2026). "The findings indicate that P. gingivalis/F. nucleatum co-infection was characterized by increased alveolar bone loss and TNF-α and IL-1β levels compared to infection by individual agents." (PMID 41228271, 2025). "In our study, Welch’s test was used to determine the significance of differences in the range of the analyzed proinflammatory cytokines, TNF-α, IL-1β and IL-6, associated with the three tested atypical pathogens and their co-infections." (PMID 40647668, 2025). "Increased proliferation of HIV in lung of persons with Mtb co-infection has been previously associated with increased TNF-α and CCL2 levels in bronchoalveolar lavage." (PMID 32373548, 2020). "The underlying conditions in co-infections are rhabdomyolysis and sickle cell disease, which result from TNF-α and RBC sequestration in skeletal muscle, increased blood viscosity, and toxins from the parasite together with lactic acidosis." (PMID 31522680, 2019). "The secretion of prostaglandin E2 (PGE2) and then stimulation of viral replication by PGE2, TNF-α, and lipopolysaccharide (LPS) were suggested as a pathogenic model for BoHV-4 and bacterial co-infection in endometritic cows." (PMID 29556236, 2018). "In summary, HIV co-infection with MTB was associated with a decrease in the amount of cytokine (TNF-α and IFN-γ) secreted for HIV-specific CD8+ T cells." (PMID 25781898, 2015). "The higher IL-10/TNF-α ratio in the group of participants with Plasmodium mono-infection than in the group with Plasmodium/helminth co-infection suggests a possible lower risk of developing clinical signs in the case of STH/P. falciparum co-infection, as demonstrated by Frosch & John." (PMID 35421083, 2022). "Alternatively, indirect activation of T cells harboring SIV may contribute to this spike in plasma viremia, as the production of TNF-α associated with Mtb co-infection can contribute to increased viral replication (34, –, 36)." (PMID 35467372, 2022). "In regard to the immunity of individual patients, a previous study showed that co-infection has been associated with a strong activation of acute phase response, such as Interleukin 6 (IL-6), Tumor necrosis factor-α (TNF-α), and IL1-β and also Th1 cytokines (IFN-γ and IL-12)." (PMID 31522680, 2019). "Alternatively, TNF-α production may be caused by bacterial (co-)infection as common in critically ill patients." (PMID 28878289, 2017). "Similarly, Strongyloides co-infection was associated with decreased frequencies of CD4+ T cells co-expressing TNF-α/IFN-γ or IL-2/IFN-γ/TNF-α at baseline in comparison to individuals with active TB only." (PMID 25211342, 2014). "CM from co-infection with both vectors expressing chimeric CD11b-scFv and TNF slightly reduced the % of AnnV+PI+ late apoptotic and AnnV−PI+ dead cells caused by SM-164, suggesting that co-infection with both vectors may reduce the infection efficacy for each alone." (PMID 39105847, 2024). "Co-infection with both viruses led to similarly lower TNFα levels, confirming the dominant attenuating effect of T209L DENV mutant." (PMID 40962941, 2025). "Guzmán-Guzmán and colleagues reported that coinfection was related to increased levels of TNF-α, mainly in patients receiving antirheumatic treatment." (PMID 41410796, 2025). "At the same time, in both patients’ groups with HIV/TB co-infection, the TNF-α levels were significantly decreased (on average by 3.3 times, p < 0.0001) when compared with groups with HIV and TB monoinfections." (PMID 38790916, 2024). "The TNF-α levels in patients with HIV/TB co-infection were also significantly lower than in patients with HIV and TB monoinfection; cytokine production was reduced by 3.1 times and 3.4 times (p < 0.0001 and p < 0.0001, respectively)." (PMID 38790916, 2024).
co-infection (continued). "We also examined the impact of index case HIV co-infection on Mtb infection as defined by various positivity endpoints using ESAT6/CFP10 responses for TNF, IL-2, and QFT-Plus IFN-γ." (PMID 39606489, 2024). "In a mouse model, co-infection with P. gingivalis and F. nucleatum led to higher releases of IL-1β and TNF-α, as well as an increase in alveolar bone resorption." (PMID 38612423, 2024). "Co-infection is rare in patients on TNF-alpha inhibitor therapy, and most cases have been reported in patients with human immunodeficiency virus (HIV)." (PMID 38496097, 2024). "Significant increases of IL-6, IL-8, TNFα, and IL-1α were observed in the vWT and S. suis co-infection group, compared to the vWT single-infection group, indicating that co-infection of PRRSV-2 and S. suis enhanced the proinflammatory cytokine expressions." (PMID 38547254, 2024). "In contrast, the co-infection of vL126A/ΔNLS with S. suis induced significantly lower-level expressions for IL-6, IL-8, TNFα, and IL-1α in comparison with the vWT and S. suis co-infection." (PMID 38547254, 2024). "Production and release of TNF-α, IL-6, and IL-10 protein 24 h after B. burgdorferi infection and coinfection was confirmed via ELISA." (PMID 37764937, 2023). "Coinfection was associated with a lower frequency of dual-function HIV specific CD4 T cells and lower CD4 IFN-γ and TNF-α production in responding cells." (PMID 37644394, 2023). "Co-infected mice exhibited decreased levels of pro-inflammatory cytokines (i.e., IFN-γ, TNF-α, and IL-12p70), whereas the level of anti-inflammatory cytokine (IL-10) was elevated in the acute phase of co-infection." (PMID 37492527, 2023). "As is consistent with these studies, our study also found that co-infection promoted TNF-α expression." (PMID 36992486, 2023). "In our experimental design, we induced inflammation using co-infection with a pathogen or its purified toxin, in addition to TNF-α, which is known to stimulate a wide inflammatory cascade through activation of the NF-κB signaling pathway." (PMID 37108065, 2023). "We analyzed the secretion of multiple cytokines/chemokines using a cytokine bead assay, and we observed reduced KC, MCP-1, RANTES, GM-CSF, IFN-β and TNF-α secretion in co-infection compared to P. aeruginosa mono-infection." (PMID 35174108, 2022). "The high IL-10/TNF-α and IL-10/IL-6 ratios observed here in participants with helminth co-infections are consistent with such observations." (PMID 35421083, 2022). "Overall, the results showed upregulation of cytokines IL-10, IFN-γ, and IL-6 and downregulation of IL-12p70, Il-2, and TNF-α during severe Babesia co-infection in mice." (PMID 35719355, 2022). "A trend towards a downregulation of TNF-α expression was observed in co-infections with intestinal parasites." (PMID 35421083, 2022). "In this study, we additionally report the regulation of proinflammatory (IL1-α, IL1-β, IL6, IL8, IL18, and TNF-α) and regulatory (IL10, IL22, IL23, and IL33) cytokines associated with single-PDCoV and -PEDV infection, as well as PDCoV/PEDV co-infection." (PMID 36376395, 2022). "The GAS-inducible upregulation of inflammatory genes, such as Nos2, as well as the secretion of TNFα and IL-1β were notably reduced or even abrogated following co-infection." (PMID 36365071, 2022). "The median TNF-α level and IL-10/IL-6 ratio were higher in subjects with STHs (p = 0.09) and P. falciparum-intestinal protozoa co-infection (p = 0.04), respectively." (PMID 35421083, 2022). "The activation of MAPK p38 in influenza virus single or co-infections with S. pneumoniae or S. aureus was shown to play an essential role in the production of cytokines, such as IFNβ, IL-1β, tumor necrosis factor α (TNFα) and IL-6, in vitro and in vivo." (PMID 34067487, 2021). "In vaccinated pigs, co-infection induced a greater PRRSV-specific TNF+ CD8+ T cell response in the BALF and an increased Ab response." (PMID 34858411, 2021).
co-infection (continued). "The intensity of brown color revealed that TNF-α and IL-1β in murine mammary gland was upregulated in the co-infection group than the H. ovis and T. pyogenes individual infectiongroups in immunohistochemical analysis." (PMID 35224069, 2021). "In our study, the expression levels of inflammatory cytokines such as IFN-β, IL-1β, and TNF-α in the trachea, lungs, and kidneys were greater in the co-infection groups, especially in the IBV/H9N2 group, than in the single-infection IBV and H9N2 groups." (PMID 35211536, 2021). "Our findings showed that while HIV-1 infection alone upregulates TNF-α production and activates NF-κB signaling, C. neoformans coinfection drastically and rapidly dampens this proinflammatory response." (PMID 33762317, 2021). "Compared with the group infected with PPRV alone, the mRNA expression levels of TNF-α, IL-6 and IL-10 were enhanced in all co-infection groups." (PMID 33827620, 2021). "We observed a significant increase in IFN-γ and TNF-α producing CD8+ T cells in animals with acute- or co- infection, in sharp contrast to their chronically infected counterparts." (PMID 33927339, 2021). "HIV–MTb co-infection also enhances the levels of pro-inflammatory cytokines such as Tumor Necrosis Factor-alpha (TNF-α) that further increases the replication of the virus and promotes the progression of the HIV to Acquired Immunodeficiency Syndrome (AIDS)." (PMID 34295314, 2021). "It is found that co-infection of PRRSV with HPS can increase the expression of pro-inflammatory cytokines such as TNF-α, IL-1β, and IL-8 in PAM cells." (PMID 34513970, 2021). "In particular, the group infected with PPRV followed by GTPV was the most significant, but compared with the group infected with GTPV alone, the mRNA expression levels of TNF-α, IL-6, and IL-10 in all co-infection groups were inhibited." (PMID 33827620, 2021). "We have previously shown that proinflammatory mediators (NOS2, IL-6, and TNF-α) increase in the heart of mice after co-infection with T. cruzi strains, and that fenofibrate is able to modulate this response." (PMID 33072115, 2020). "Bacterial mono- or co-infection strongly induce the expression of TNF-α, in particular in hMdM cells." (PMID 32316261, 2020). "Coinfection with HIV was associated with higher levels of sFas, TNF-α, and sPD-L1 compared to healthy controls (P < 0.005)." (PMID 30815625, 2019). "LZD, vancomycin, or clindamycin significantly decreased pulmonary IL-6 and mKC levels at 4 h and the IFN-γ level at 24 h after MRSA co-infection, while the levels of IL-1β, TNF-α, and IL-12 were similar to those of the placebo group." (PMID 31849655, 2019). "Coinfection with HIV was associated with higher levels of sFas, TNF-α, and sPD-L1 (P < 0.005), and higher levels of the pro-inflammatory cytokines IL-6, IL-8, and IL-12p70 (P < 0.05) compared to healthy controls." (PMID 30815625, 2019). "Significant positive correlations were observed between IFN-γ with TNF-α (Spearman r = 0.847) and IL-6 with IL-10 (Spearman r = 0.557) among co-infection." (PMID 31687034, 2019). "In opportunistic HIV co-infection, high levels of serum TNF-α and IFN-γ are the predictors for onset of acute VL infection." (PMID 31024534, 2019). "In the absence of NF-κB signaling, proteasomal degradation of C/EBPβ is increased by a JNK-independent mechanism and promotes death from TNF-α, which suggests that we can use C/EBPβ as a target protein for the treatment of IL-17 outbreaks on co-infection." (PMID 31803158, 2019). "Significant positive correlations were identified between IFN-γ verses TNF-α and IL-6 verses IL-10 in co-infection (Spearman’s P < 0.05)." (PMID 31687034, 2019). "This review briefly discusses patterns of selected cytokine (IL-6, IL-8, IL-10, TNF-α and INF-γ) responses associated with infections caused by Plasmodium, intestinal parasites as well as a Plasmodium-helminth co-infection." (PMID 29970128, 2018).
co-infection (continued). "The levels of lung TNF-α elevate during a Spn-influenza co-infection, and its depletion exacerbates Spn infection." (PMID 30333833, 2018). "Our study demonstrated that co-infection significantly upregulated TNF-α while parasite replication increased more than in mono-infected cultures." (PMID 30081942, 2018). "The same pattern was found for TNF-α, levels of which were significantly increased in co-infection with 1.86 fold (p = 0.007) and 2.16 fold (p = 0.001) as compared to CHIKV and DENV mono-infections, respectively." (PMID 28644900, 2017). "We found that simultaneous co-infections result in the selective inhibition of CHIKV replication and an increase in cytokines associated with disease severity such as TNF-α and IL-6." (PMID 28644900, 2017). "Decreased levels of IFN-γ, TNF, IL-6, and IL-10 were observed in the serum of co-infected groups, demonstrating a modulation of Malaria immune response by Leishmania co-infections." (PMID 27446022, 2016). "It is concluded that Matrine possesses activity against PRRSV/PCV2 co-infection in vitro and suppression of the TLR3,4/NF-κB/TNF-α pathway as an important underlying molecular mechanism." (PMID 27080155, 2016). "Outgrowth induces a strong immune response including neutrophil recruitment and TNF-α induction, which we show contribute to bacterial control and are protective in coinfection." (PMID 26265006, 2015). "In summary, HIV co-infection with MTB was associated with a decrease in the amount of cytokine (IFN-γ, TNF-α and IL-2) secreted for HIV-specific CD4+ T cells." (PMID 25781898, 2015). "HIV co-infection was associated with an increased frequency of CMV-specific IFN-γ-only and TNF-α-only CD4+ cells compared with PPD." (PMID 26417433, 2015). "Fortunately, TNF is now approved for use in special circumstances (possibly HIV-HBV coinfection) among children from the age of 2 years." (PMID 23691352, 2013). "Single nucleotide polymorphism of TNF-α and IL-10 genes studied in healthy controls and patients with HIV-HCV coinfection." (PMID 23840511, 2013). "Co-infection with these deletion mutants blocked IFN-α or TNF induction in pDCs infected with Heat-VAC to the same extent as co-infection with WT vaccinia (data not shown)." (PMID 22606294, 2012). "Co-infection also led to elevated serum levels of TNF compared to the levels observed in mice infected with L. major alone, which may contribute to a more effective control of the Leishmania parasite." (PMID 40720541, 2025). "The study also aimed to explore the role of IFN‐γ and TNF in the context of co‐infection." (PMID 40135792, 2025). "Co-infection of SCoV2 and H1N1 caused an elevation in the IL-6 and IL-8 concentrations compared with the SCoV2 single infections, while the co-infection of SCoV2 and H5N1 caused an elevation in the IL-6, IL-8, IP-10, RANTES, and TNF concentrations than SCoV2 infection." (PMID 40431161, 2025). "Coinfection suppresses the type I interferon (IFN) response, activates the inflammasome and associated pathways, and concurrently triggers the massive secretion of pro-inflammatory cytokines (e.g., IL-6, TNF-α, IL-1β)." (PMID 41561948, 2025). "Similar patterns of immune dysregulation have been observed in other HIV-parasitic co-infections, such as schistosomiasis and soil-transmitted helminths, where elevated TNF-α and IL-6 persist, even in individuals on ART, indicating persistent immune activation." (PMID 40046043, 2025). "Our findings revealed that co-infection with T. solium significantly influenced immune responses, with TNF-α levels showing a strong negative association with CD4 counts, while this association was positively modulated by CC status." (PMID 40046043, 2025). "Our findings suggested that HIV co-infection in LTB-positive individuals is associated with the diminished production of PPD-induced Th1 (IFN-gamma and IL-2) cytokines by PBMCs and in the plasma level of IL-2 and proinflammatory cytokines (IL-6 and TNF-alpha)." (PMID 39514524, 2024).